KIF20A (kinesin family member 20A)
Diseases named in the same sentence as KIF20A in open-access papers (continued):
Sharing a sentence is not in itself a finding about the gene and the disease.
prostate carcinoma (14 papers, 2019 to 2025). A carcinoma that arises from epithelial cells of the prostate gland. "Our studies have demonstrated that KIF20A is abnormally highly expressed in prostate cancer tissues and is associated with adverse prognosis of PCa patients and knockdown of KIF20A can inhibit the proliferation and invasion of prostate cancer cells." (PMID 31565099, 2019). "In conclusion, our study demonstrates for the first time that KIF20A is highly expressed in prostate cancer and is associated with poor prognosis." (PMID 31565099, 2019). "In the FH cohort, KIF20A expression was significantly upregulated in postchemotherapy prostate cancer tissues." (PMID 34593983, 2023). "Among these genes, expressions of AURKB and KIF20A was a significantly poor prognostic factors for prostate cancer recurrence, and we focused on these two genes." (PMID 34593983, 2023). "KIF20A activates the autocrine of androgen receptors, promotes prostate cancer development and is a promising target for cancer immunotherapy." (PMID 36524130, 2022). "KIF20A, a kinesin, promotes the progression of castration-resistant prostate cancer through autocrine activation of the androgen receptor." (PMID 36531013, 2022). "MTT assay, transwell assay, and colony formation assay in vitro and tumor formation assay in vivo were performed to evaluate the biological behavior of KIF20A in prostate cancer." (PMID 31565099, 2019). "Knocking down KIF20A suppressed the proliferation, migration, and invasion of the prostate cancer cell both in vitro and in vivo." (PMID 31565099, 2019). "In the latest published study on biomarkers of prostate cancer, hub genes such as KIF20A and CDCA8 are associated with adverse BCR-free survival of PCa patients and have better specificity and sensitivity in the diagnosis of prostate cancer." (PMID 31565099, 2019). "At the same time, we have demonstrated that KIF20A can promote the proliferation and invasion of prostate cancer cells in vitro and promote tumor growth by using the xenograft model." (PMID 31565099, 2019). "In our study, transwell experiments also found that knockdown of KIF20A significantly inhibited the migration and invasion of prostate cancer cells." (PMID 31565099, 2019). "AURKB and KIF20A were highly expressed in cabazitaxel-resistant prostate cancer cells." (PMID 36798768, 2023). "Higher expression of AURKB and KIF20A was a poor prognostic factor of TGCA prostate cancer cohort." (PMID 34593983, 2023). "We also investigated the role of KIF20A in CBZ-resistant prostate cancer." (PMID 34593983, 2023). "However, the significance of KIF20A expression in tumor progression or chemoresistance in prostate cancer has been unclear." (PMID 34593983, 2023). "Similarly, we found that KIF20A is highly expressed in prostate cancer by immunohistochemistry and Western blotting, and bioinformatics analysis found that high expression of KIF20A is associated with biochemical recurrence in PCa patients." (PMID 31565099, 2019). "But the association between the KIF20A clinical role and prostate cancer (PCa) has not been reported yet." (PMID 31565099, 2019). "With regard to that, we also used in vitro and in vivo experiments to demonstrate whether KIF20A regulated proliferation, migration, and invasion of prostate cancer cells." (PMID 31565099, 2019). "In summary, KIF20A may be used as a tumor antigen or a potential drug target to improve the survival rate of prostate cancer patients in immunotherapy and precision treatment." (PMID 31565099, 2019). "However, research of KIF20A's potential roles on prostate cancer has been always been a blank." (PMID 31565099, 2019). "However, the role of KIF20A in the development and progression of prostate cancer is unclear." (PMID 31565099, 2019).
prostate carcinoma (continued). "Our data demonstrated that the high expression of KIF20A was associated with poor clinical outcome and targeting KIF20A could reduce proliferation, migration, and invasion of the prostate cancer cell, indicating that KIF20A might be a potential prognostic and therapeutic target for PCa patients." (PMID 31565099, 2019). "Hence, KIF20A may be a potential therapeutic target for the treatment of prostate cancer." (PMID 31565099, 2019). "Pimozide could be a promising drug to overcome taxane cabazitaxel (CBZ) resistance in docetaxel-resistant prostate cancer (CRPC) patients by targeting AURKB and KIF20A." (PMID 36798768, 2023). "FOXM1 and KIF20A exhibited consistent and highly correlated overexpression in prostate cancer cells and tissues, highly expressed FOXM1 may help promote docetaxel resistance by inducing KIF20A expression." (PMID 36798768, 2023). "CBZ-resistant prostate cancer tissues in our institution had higher AURKB and KIF20A expression." (PMID 34593983, 2023). "Secondly, although we confirmed that KIF20A can promote the migration and invasion of prostate cancer cells in vitro, we did not further confirm at the in vivo level." (PMID 31565099, 2019).
lung adenocarcinoma (13 papers, 2018 to 2025). A carcinoma that arises from the lung and is characterized by the presence of malignant glandular epithelial cells. "KIF20A also influences lipid metabolism and antioxidant defenses, thereby affecting resistance to oxidative stress and drug treatment in lung adenocarcinoma." (PMID 41013841, 2025). "KIF20A is upregulated in lung adenocarcinoma, and it is related to cell proliferation and apoptosis." (PMID 36661515, 2023). "However, little is known about the role of KIF20A in lung adenocarcinoma (LUAD)." (PMID 30105795, 2018).
cervical cancer (12 papers, 2016 to 2026). A primary or metastatic malignant neoplasm involving the cervix. "Furthermore, survival analysis revealed that expression of the KIF20A protein was an independent novel biomarker associated with poorer survival outcomes in cervical cancer patients." (PMID 27941992, 2016). "In this study, we found that KIF20A protein expression is significantly associated with a number of advanced-disease factors, which suggests that it plays an important role in carcinogenesis and aggressiveness in cervical cancer." (PMID 27941992, 2016). "Further analysis revealed that miR-204 was a target of UCA1, UCA1 sponged miR-204 thus increased KIF20A in cervical cancer." (PMID 36798768, 2023). "miR-153 promotes downreulation of KIF20A and inhibits migration and invasion of cervical cancer cells." (PMID 36158686, 2022). "Through bioinformatics methods and meta-analysis, KIF20A expression was found to significantly vary among 363 normal tissues and cervical cancer tissues and thus considered correlated with cervical cancer development." (PMID 34414195, 2021). "In conclusion, our study suggests that the expression levels of KIF20A contribute to progression of cervical cancer." (PMID 27941992, 2016). "We found that KIF20A expression is upregulated at both the transcriptional and translational levels in human cervical cancer." (PMID 27941992, 2016). "We examined the mRNA and protein levels of KIF20A in eight cervical cancer cell lines and eight paired cervical cancer samples, compared with normal cervical epithelial cells and adjacent normal cervical tissues, respectively." (PMID 27941992, 2016). "All eight cervical cancer cell lines exhibited significantly elevated protein and mRNA (up to 5-fold) levels of KIF20A compared with normal cervical epithelial cells (P < 0.05)." (PMID 27941992, 2016). "The mRNA and protein expression levels of KIF20A were significantly elevated in cervical cancer cell lines and lesions compared with normal cells and corresponding normal tissues (P < 0.05)." (PMID 27941992, 2016). "The kinesin family member 20a (KIF20A) protein has been implicated in the development and progression of many human cancers; however, its precise function and role in cervical cancer remain largely unclear." (PMID 27941992, 2016). "KIF20A was a target of circ_0005576 in facilitating cervical cancer progression." (PMID 36798768, 2023). "However, the precise mechanisms by which KIF20A impacts cervical cancer progression and patient prognosis requires further investigation." (PMID 27941992, 2016). "KIF20A aberrant expression is a novel independent unfavorable prognostic factor and may present a potential therapeutic target for cervical cancer." (PMID 27941992, 2016). "Interestingly, KIF20A protein overexpression can serve as a good prognostic marker of poor postoperative OS for cervical cancer patients with a positive pelvic lymph node status." (PMID 27941992, 2016). "In addition to KIF20A expression, we found that the SCC-Ag was an independent prognostic factor associated with poorer survival outcomes in cervical cancer patients." (PMID 27941992, 2016). "However, a detailed understanding of the mechanisms of KIF20A in regulating PLNM of early-stage cervical cancer is still necessary." (PMID 27941992, 2016). "Thus, UCA1 upregulated KIF20A expression to exacerbate cervical cancer via sponging miR-204." (PMID 36798768, 2023). "Therefore, KIF20A-targeted treatment may be of great significance and may serve as a potential method for cervical cancer or its radiotherapy." (PMID 34414195, 2021). "Moreover, functional analysis of KIF20A protein modification during tumor proliferation and metastasis is required to provide information on its functional significance in the progression of cervical cancer." (PMID 27941992, 2016).
cervical cancer (continued). "In this study, aberrant KIF20A protein expression was observed in HPV-positive cervical cancer samples (31.9%), whereas HPV-negative specimens expressed low levels of KIF20A (16.6%)." (PMID 27941992, 2016). "KIF20A expression was also significantly higher in the eight human cervical cancer tissues compared with the paired attached non-cancerous cervical tissues at both the transcriptional (up to 9-fold) and translational levels (P < 0.05)." (PMID 27941992, 2016). "In addition, KIF20A regulated by lncRNA UCA1, may promote cell proliferation during the growth of cervical cancer cells." (PMID 35410446, 2022).
cervical squamous cell carcinoma (12 papers, 2016 to 2025). A squamous cell carcinoma arising from the cervical epithelium. "Weijing Zhang and the team have shown that elevated KIF20A expression in early-stage cervical squamous cell carcinoma is linked to HPV infection, advanced stage, and heightened risk of recurrence and metastasis, underscoring its role as an independent prognostic indicator and therapeutic target." (PMID 39272816, 2024). "KIF20A protein expression in early-stage cervical squamous cell cancer was significantly associated with aggressive clinicopathological features and it is a good predictor for HPV infection, FIGO stage, lymphovascular space involvement, and pelvic lymph node metastasis." (PMID 27941992, 2016). "This study aimed to investigate the expression profile and prognostic value of KIF20A in patients with early-stage cervical squamous cell carcinoma." (PMID 27941992, 2016). "Correlation between KIF20A protein expression and the clinicopathological characteristics of patients with early-stage cervical squamous cell carcinoma." (PMID 27941992, 2016). "Clinicopathological characteristics and tumor expression of KIF20A in patients with early-stage cervical squamous cell carcinoma." (PMID 27941992, 2016). "Immunohistochemistry was performed to detect the expression of KIF20A in paraffin-embedded specimens from 169 early-stage cervical squamous cell carcinoma patients." (PMID 27941992, 2016). "Correlation between KIF20A protein expression and the clinicopathologic features of patients with early-stage cervical squamous cell carcinoma." (PMID 27941992, 2016). "Other cancers, such as cervical squamous cell carcinoma and endocervical adenocarcinoma, revealed a striking median fold change of 74.08, indicating a profound differential in KIF20A expression that may correlate with disease severity or prognosis." (PMID 39272816, 2024). "Furthermore, KIF20A protein was identified as an independent marker for predicting the clinical outcome of early-stage cervical squamous cell cancer patients." (PMID 27941992, 2016). "Another Kinesin family member, KIF20A, has been correlated with HPV infection, clinical stage, tumor recurrence, lymphovascular space involvement, pelvic lymph node metastasis, and poor outcome in early-stage cervical squamous cell carcinoma patients." (PMID 41516135, 2025). "Our results illustrate that elevated KIF20A expression correlates with HPV infection, clinical stage, tumor recurrence, lymphovascular space involvement, pelvic lymph node metastasis, and poor outcome in early-stage cervical squamous cell carcinoma patients." (PMID 27941992, 2016).
liver cancer (12 papers, 2016 to 2025). An epithelial or non-epithelial malignant neoplasm that arises from the liver. "KIF20A, also referred to as Kinesin Family 20A, has been implicated in the progression of several malignancies, including bladder, prostate, pancreatic ductal adenocarcinoma, and liver cancer." (PMID 40600015, 2025). "In liver cancer, deleting KIF20A expression inhibited HCC cell proliferation and enhanced HCC cell chemical sensitivity to cisplatin and sorafenib." (PMID 37504265, 2023). "In liver cancer, low expression of KIF20A inhibits cell proliferation, promotes chemosensitivity, and is associated with a better prognosis." (PMID 36531013, 2022). "We then examined the relationship between KIF20A expression level and migratory capacity of a cell using eight different liver cancer cell lines." (PMID 30813560, 2019). "In addition, KIF20A is a candidate biomarker for prognosis of non-small cell lung cancer (NSCLC), glioblastoma and liver cancer." (PMID 33941190, 2021).
ovarian carcinoma (12 papers, 2019 to 2024). A malignant neoplasm originating from the surface ovarian epithelium. "Moreover, our data support that Cyclin F and KIF20A are involved in FOXM1-mediated ovarian cancer formation and development, and high Cyclin F and KIF20A expression was associated with poor prognosis in patients with ovarian cancer." (PMID 36359787, 2022). "Han Li’s study connects overexpression of KIF20A in epithelial ovarian cancer with advanced stages, metastasis, recurrence, and chemoresistance, establishing it as a significant independent risk marker and promising prognostic biomarker." (PMID 39272816, 2024). "In ovarian cancer, KIF20A overexpression conferred epithelial ovarian cancer cells resistance to cisplatin." (PMID 34491228, 2021). "Our laboratory also demonstrated that Cyclin F and KIF20A are involved in FOXM1-mediated ovarian cancer cell proliferation and metastasis, and high expression of Cyclin Fand KIF20A was associated with poor prognosis in patients with ovarian cancer." (PMID 36359787, 2022). "As a FOXM1 target gene, KIF20A increases the proliferation and invasion of ovarian cancer cells." (PMID 35410446, 2022). "In conclusion, by using a systematic approach of evaluating and prioritizing TAAs, we have identified KIF20a, CT45, and LY6K to be highly suitable targets for targeted T cell therapy in ovarian cancer." (PMID 36768616, 2023). "Then, we demonstrated that exosomes secreted by HO-ADSCs (HO-ADSC exosomes) enhanced ovarian cancer cell function, and further mechanistic studies showed that the FOXM1, Cyclin F, KIF20A, and MAPK signaling pathways were involved in this process." (PMID 36359787, 2022). "In addition, we demonstrated that HO-ADSC exosomes promote the growth and metastasis of ovarian cancer cells via a mechanism dependent on the FOXM1, Cyclin F KIF20A, and MAPK signaling pathways." (PMID 36359787, 2022).
renal clear cell carcinoma (10 papers, 2020 to 2023). "Moreover, overexpression of KIF20A can promote tumor proliferation and invasion in renal clear cell carcinoma and is associated with poor clinical outcome." (PMID 37051238, 2023). "KIF20A was closely associated with immune infiltration in clear cell renal cell carcinoma (ccRCC)." (PMID 36909154, 2023). "KIF20A had a strong positive association with Th2 cells, Treg cells, and macrophages but a negative association with Th17 cells, mast cells, and NK cells in renal clear cell carcinoma." (PMID 35359374, 2022). "Interference with KIF20A can significantly inhibit proliferation, invasion and migration of renal clear cell carcinoma." (PMID 33941190, 2021). "The PPI network in GSE121711 showed that KIF20A was a hub gene of renal clear cell carcinoma." (PMID 37310408, 2023).
cholangiocellular carcinoma (6 papers, 2011 to 2024). "KIF20A is related to the specific immune response of cholangiocarcinoma." (PMID 37504265, 2023).
lymph node metastasis (6 papers, 2016 to 2025). "Patients with high KIF20A expression showed increased propensity for lymph node metastasis, poor differentiation, and advanced-stage disease." (PMID 41267030, 2025). "KIF20A was significantly upregulated in NSCLC versus adjacent tissues (63.2% vs. 13.2%, P < 0.001) and associated with lymph node metastasis, poor differentiation, and advanced stage (P < 0.05)." (PMID 41267030, 2025). "In univariate analysis, higher KIF20A expression, positive lymph node metastasis, advanced T stage and TNM stage were significantly correlated with worse prognosis." (PMID 30105795, 2018). "Additionally, high KIF20A expression was associated with poorer 5-year OS and PFS in both the entire cohort of patients and the subgroups with T3–T4 disease, lymph node metastasis, clinical stage III–IV disease and CCRT subgroups." (PMID 28081138, 2017).